PCP2 (Purkinje cell protein 2)
Description:
May function as a cell-type specific modulator for G protein-mediated cell signaling.
Synonyms: MGC41903; GPSM4; PCD5
Tractability: No criterion of Open Targets' tractability assessment is met for any kind of drug.
Gene: Protein-coding gene on chromosome 19 (7,631,611 to 7,633,719, reverse strand). Ensembl gene ENSG00000174788.
Subcellular location (Human Protein Atlas): Nuclear speckles; Vesicles
Pathways (Reactome):
Signal Transduction: G alpha (i) signalling events
Gene Ontology:
Molecular function: protein binding; guanyl-nucleotide exchange factor activity; GTPase regulator activity
Genetic constraint (gnomAD): Loss-of-function variants: 21 observed, 13.45 expected, observed/expected ratio (o/e) 1.56, 90% interval 1.09 to 1.93. The synonymous counts are far from expectation, so gnomAD's model fits this gene poorly and the ratio says little. Missense variants: 202 observed, 159.35 expected, observed/expected ratio (o/e) 1.27, 90% interval 1.13 to 1.42. Synonymous variants: 85 observed, 60.21 expected, observed/expected ratio (o/e) 1.41, 90% interval 1.18 to 1.69.
Homologues: Orthologues: chimpanzee PCP2 (99% identical), macaque PCP2 (98% identical), dog PCP2 (86% identical), rabbit PCP2 (84% identical), pig PCP2 (83% identical), guinea pig PCP2 (75% identical), rat Pcp2 (75% identical), mouse Pcp2 (74% identical).
Diseases named in the same sentence as PCP2 in open-access papers:
PCP2 is named in the same sentence as 17 diseases in open-access papers, as found by Europe PMC text mining. Sharing a sentence is not in itself a finding about the gene and the disease. The quoted sentences say what the papers report.
Ataxia (5 papers, 2016 to 2024). Ataxia refers to impaired coordination of voluntary muscle movement. "Pcp2-cko mice demonstrated cerebellar atrophy, ataxia and progressive Purkinje cells loss which were accompanied by increased apoptosis and neuroinflammation." (PMID 39521780, 2024). "We have previously demonstrated, in a different rodent model of cerebellar ataxia, that the expressions of Calb1, Pcp2 and Grid2, as well as that of some other genes highly expressed in PCs, significantly reduce as the disease phenotype progresses." (PMID 27013529, 2016). "To explore the role of SEL1L-HRD1 ERAD in cerebellar ataxia, we generated Sel1LPcp2Cre mice with Purkinje cell–specific deletion of Sel1L by crossing Sel1Lfl/fl mice with a transgenic mouse expressing Cre recombinase driven by the promoter of Purkinje cell protein 2 (Pcp2)." (PMID 39352758, 2024).
Anxiety (3 papers, 2020 to 2025). Intense feelings of nervousness, tension, or panic often arise in response to interpersonal stresses. "In a mutant mouse model with inactivation of the Pcp2 allele, sex-specific effects were measured in anxiety behaviors, however, these phenotypes were not linked to sex-specific differences in Pcp2 expression." (PMID 39741564, 2024).
head and neck cancer (3 papers, 2018 to 2024). A primary or metastatic malignant neoplasm affecting the head and neck. "While research on the impact of PCP2 in cancer is limited, it has been proposed as a potential therapeutic target for neuropathic pain associated with head and neck cancer." (PMID 38674408, 2024).
breast carcinoma (2 papers, 2021 to 2022). "Thus far, the relationship of TNN, TRBV7-4, and PCP2 with cancer has not been reported, and our results suggest that these genes, as core pyroptosis genes, have important associations with breast cancer development and the immune microenvironment." (PMID 36158689, 2022).
neuropathy (2 papers, 2018 to 2023). A disorder affecting the nervous system that manifests with pain, tingling, numbness, and/or muscle weakness. "Using GWA study, we found four SNPs in four genes (SNX8; PCP2; KNG1; and RORA) to be statistically significantly associated with neuropathy." (PMID 29884837, 2018).
colon cancer (1 paper, 2016). "Protein tyrosine phosphatase receptor type U (PTPRU), also known as Purkinje cell protein 2 (PCP2), is a PTP that has been shown to negatively regulate the growth and migration of colon cancer cells." (PMID 27761023, 2016).
malnutrition (1 paper, 2023). Inadequate nutrition resulting from poor diet, malabsorption, or abnormal nutrient distribution. "Since Pcp2-Cre is not widely active at P1, in order to investigate the role of Ptrh2 during early stages of PC differentiation, we went to an in vitro system to avoid the effect of malnutrition and dystrophy observed in Ptrh2−/− mice as a confounding factor." (PMID 36219306, 2023).
retinal degeneration (1 paper, 2021). Degeneration of the retina. "Indeed, a clear cytoplasmic signal for Pcp2 and Goα was detected in the inner nuclear layer (INL) of WT and mut retinas both at the early (postnatal day [P]14) and at later stage (P60) of retinal degeneration, when most photoreceptors have already been lost." (PMID 33665228, 2021).
spastic ataxia (1 paper, 2025). "We also addressed the potential implications of our findings on the pathogenesis of ANKFY1 in recessive spastic ataxia, such as glial cell activation, changes in the collagen ligand integrin, and the regulation of Rho-GTPase and PCP2-mediated loss of Purkinje cells." (PMID 40594855, 2025). "Because of the specific expression of PCP2 in Purkinje cells, we postulated that ARHGDIB and PCP2 are the critical target proteins related to ANKFY1 deficiency-induced spastic ataxia." (PMID 40594855, 2025).
cancer (5 papers, 2015 to 2024). A tumor composed of atypical neoplastic, often pleomorphic cells that invade other tissues. "PCP2 is a member of the R2B subfamily and is considered a tumor suppressor that influences the development of many cancers." (PMID 35693786, 2022). "Patients with cancer with high expression of the PCP2 and TNN genes were probably sensitive to AS605204 and FK886 and resistant to XAV939." (PMID 36158689, 2022). "Meanwhile, protein tyrosine phosphatase receptor type U (PTPRU), also known as Purkinje cell protein 2 (PCP2), has been shown to function as a regulator of adhesion and proliferation in certain cancer cell types." (PMID 26587830, 2015).
tumor (3 papers, 2021 to 2022). "Another notable example is hsa-miR-574–5p which promotes metastasis in NSCLC by targeting PCP2 in tumor tissues and has been proposed as an early stage NSCLC serum biomarker." (PMID 35147498, 2022).
infection (1 paper, 2016). The state of being infected such as from the introduction of a foreign agent such as serum, vaccine, antigenic substance or organism. "Transgene and control viral vectors were injected into the deep cerebellar nuclei of Npc1 flox/-;Pcp2-Cre mice at 6 weeks and animals were examined four weeks post-infection." (PMID 27152617, 2016).
PCP2 also shares sentences with these, for which no sentence is quoted: cerebellar ataxia (2 papers); congenital hypothyroidism (1); ovarian carcinoma (1); prostate carcinoma (1); triple-negative breast carcinoma (1).